HDAC10 (histone deacetylase 10)
Diseases named in the same sentence as HDAC10 in open-access papers (continued):
Sharing a sentence is not in itself a finding about the gene and the disease.
lung carcinoma (continued). "In addition, HDAC10 negatively regulates lung cancer development by promoting protein kinase B (AKT) phosphorylation." (PMID 38956592, 2024). "The tumor-suppressor activity of HDAC10 in lung cancer appears to be connected to the KRAS pathway." (PMID 39409979, 2024). "HDAC10 regulates the stemness characteristics of lung cancer cells." (PMID 37171044, 2023). "Similarly, in lung cancer cells, HDAC10 was observed to localize in the cytoplasm, while its detection was predominantly nuclear in adjacent normal cells." (PMID 35988653, 2022). "HDAC10 plays a crucial role in unchecked cell progression, since deletion of HDAC10 induces blockade at mitotic entry and thus restrains cell proliferation in human lung cancers." (PMID 34395273, 2021). "For example, HDAC10 promotes cell proliferation through activation of AKT in lung cancer." (PMID 32373519, 2020). "In addition, HDAC10 is highly expressed in lung cancer tissues and can promote lung cancer proliferation." (PMID 31451695, 2019). "This study suggests that HDAC10 expression and localization may serve as valuable prognostic markers or potential therapeutic targets in patients with lung cancer." (PMID 27449083, 2016). "We found that HDAC10 and Mut505-511 also promoted the growth of lung cancer H460 cells." (PMID 27449083, 2016). "Next, we focused on how HDAC10 regulates lung cancer cell growth and survival." (PMID 27449083, 2016). "In this study, we found that HDAC10 is highly expressed in lung cancer tissues." (PMID 27449083, 2016). "HDAC10 localization in cancer is unknown, and we report for the first time that HDAC10 is located in the cytoplasm in lung cancer cells." (PMID 27449083, 2016). "This study reveals that HDAC10 functions in lung cancer cell growth and survival and highlights the promise HDAC10 inhibition holds for improving survival times and eliminating drug resistance in lung cancer." (PMID 27449083, 2016). "We found that HDAC10 knockdown decreases AKT phosphorylation and that overexpression of AKT rescues the cell cycle arrest and apoptosis elicited by HDAC10 knockdown, suggesting that AKT is associated with the function of HDAC10 in lung cancer." (PMID 27449083, 2016). "We subsequently studied how depletion of HDAC10 affects the behaviour of lung cancer cells." (PMID 27449083, 2016). "The results reveal that in all three lung cancer cell lines, HDAC10 resided in the cell cytoplasm." (PMID 27449083, 2016). "We have sequenced HDAC10 coding region in the A549, H358 and H460 cancer cell lines and found that its NLS was not mutated in these cell lines, which raises the question of how HDAC10 localization is modified in lung cancer." (PMID 27449083, 2016). "Finally, we confirmed that HDAC10 promoted lung cancer proliferation in a mouse model." (PMID 27449083, 2016). "In contrast, in lung cancer cells where SPARC protein expression is low, HDAC10 depletion had minimal effect on colony or spheroid growth." (PMID 38650694, 2024). "By targeting AKT, HDAC10 affects the expression of B-cell lymphoma-2 (BCL2) as well as BCL2 antagonist/killer (BAK), which induces apoptosis in lung carcinoma." (PMID 33997894, 2021). "These processes contributes to the growth of lung cancer spheres via SOX9-mediated stem-like properties, suggesting that HDAC10-TGF-β-SOX9-SLUG/CD44 axis plays an essential role in lung adenocarcinoma." (PMID 33997894, 2021). "The signaling pathways: HDAC10-let-7f-2/miR-98-HMGA2-cyclin A2 arrests the G2/M transition and finally inhibits lung cancer cell proliferation." (PMID 33997894, 2021). "The changes in the levels of these proteins were consistent with and supported the results of previous functional assays, suggesting that HDAC10 exerts regulatory effects on the levels of AKT, particularly the phosphorylated form of AKT, in lung cancer cells." (PMID 27449083, 2016). "However, whether HDAC10 functions in lung cancer is unknown." (PMID 27449083, 2016).
lung carcinoma (continued). "Thus, this study reveals HPD as a novel regulator of LKB1–AMPK signaling-mediated HDAC10 nuclear location, which contributes to G6PD expression in promoting tumor growth, which is a promising target for lung cancer treatment." (PMID 31285420, 2019). "Statistical analysis revealed that the levels of HDAC10 in lung cancer tissue were significantly higher than in normal tissue." (PMID 27449083, 2016). "Among them, histone deacetylase 10 (HDAC10), a member of class II HDACS, may play a role as a transcriptional modulator in the nucleus and is responsible for lung cancer progression and poor prognosis." (PMID 20409316, 2010). "However, due to the lack of public ChIP‐Seq data of HADC10 in lung cancer tissues/cells, our regulatory targets of HDAC10 have not been confirmed." (PMID 37408139, 2023).
gastric cancer (9 papers, 2015 to 2023). A primary or metastatic malignant neoplasm involving the stomach. "Decreases in HDAC10 activity have been correlated with more aggressive malignancies in B lymphocyte and have been linked to metastasis in gastric cancer and squamous cell carcinomas." (PMID 37637416, 2023). "Up-regulated HDAC10 is associated with favorable overall survival (OS) in colon cancer, gastric cancer, RCC and NSCLC patients." (PMID 33997894, 2021). "Among the class II HDAC family, HDAC10 is significantly correlated with poor prognosis in renal cancer, melanoma and gastric cancer patients." (PMID 32373519, 2020). "In gastric cancer cells, HDAC10 was found to regulate the expression of thioredoxin interaction protein (TXNIP), indicating an importance in response to oxidative stress, and knockdown of HDAC10 resulted in accumulation of ROS and cell death." (PMID 25915736, 2015). "HDAC10 also serves as a new therapeutic target in ovarian and gastric cancers." (PMID 37171044, 2023). "HDAC10 were also found to be prognostic markers for gastric cancer and colon cancer." (PMID 34308568, 2021). "However, HDAC10 was shown to be important in regulating the production ofreactive oxygen species (ROS) in gastric cancer, and its inhibition led to theaccumulation of ROS, triggering the intrinsic apoptotic pathway." (PMID 32022099, 2020).
lung adenocarcinoma (7 papers, 2021 to 2024). A carcinoma that arises from the lung and is characterized by the presence of malignant glandular epithelial cells. "The authors found an increased number of highly tumorigenic and strain-like lung adenocarcinoma cells in Hdac10-deleted tumors compared to Hdac10 wild-type tumors." (PMID 36263432, 2022). "HDAC-10 deletion accelerates early-stage KRAS-driven lung adenocarcinoma, increases macrophage infiltration within the tumor microenvironment, and shortens the survival time in mice." (PMID 36263432, 2022). "In contrast, HDAC10 suppresses cancer cell growth in other malignant tumors, including lung adenocarcinoma and renal cell carcinoma (RCC)." (PMID 33997894, 2021). "In lung adenocarcinoma, SOX9, SLUG and CD44 are activated by the down-regulation of HDAC10 and stimulation of TGF-β, which mediates CSC-related cancer progression." (PMID 33997894, 2021). "In addition, HDAC10 overexpression seem did not alter the major malignant phenotypes of lung adenocarcinoma cell lines, including proliferation and migration." (PMID 37408139, 2023). "The expression of SOX9 is significantly increased in HDAC10-depleted tumor cells, TGFβ pathway-related genes are enriched in HDAC10 knocked out tumor cells, and activation of TGFβ signaling contributes to the induction of SOX9 in HDAC10 knocked out lung adenocarcinoma cells." (PMID 36171897, 2022).
melanoma (7 papers, 2017 to 2025). A malignant, usually aggressive tumor composed of atypical, neoplastic melanocytes. "Our work indicates that the growth inhibition of melanoma cells is closely linked to SPARC upregulation following stable HDAC10 depletion." (PMID 38650694, 2024). "Supporting this hypothesis, stable HDAC10 depletion in melanoma cells caused remarkable increases in the LC3 autophagic puncta formation and accumulation, indicating an autophagy-like change." (PMID 38650694, 2024). "However, since both cell lines are sensitive to PLX4032, it remains to be conclusively determined whether HDAC10 depletion inherently alters melanoma cell susceptibility to BRAFi." (PMID 38650694, 2024). "HDAC10 and SPARC are implicated in chemotherapy response across different types of cancer, but their roles in BRAFi resistance in melanoma are unexplored." (PMID 38650694, 2024). "Further, when exposed to PLX4032, HDAC10-depleted melanoma cells exhibited more pronounced inductions of both SPARC protein and mRNA." (PMID 38650694, 2024). "Our work reveals the role of HDAC10 in gene regulation through indirect histone modification and suggests a potential therapeutic strategy for melanoma or other cancers by targeting HDAC10 and SPARC." (PMID 38650694, 2024). "Our study also demonstrates that the expression levels of both HDAC10 and SPARC respond to the activity state of mutated BRAF in melanoma cells." (PMID 38650694, 2024). "In support of this notion, the level of endogenous HDAC10 protein is statistically inversely correlated with endogenous SPARC protein expression in a panel of melanoma cell lines." (PMID 38650694, 2024). "Collectively, HDAC10 depletion suppresses melanoma cell growth, at least in part, by an increase in SPARC expression." (PMID 38650694, 2024). "Here, we demonstrate that histone deacetylase 10 (HDAC10) is a key regulator of SPARC expression in melanoma cells." (PMID 38650694, 2024). "In summary, our studies reveal that HDAC10 plays a critical role in the regulation of SPARC expression in the melanoma cells." (PMID 38650694, 2024). "The depletion of HDAC10 has a minimal effect on apoptosis and cell cycle progression in melanoma cells." (PMID 38650694, 2024). "In melanoma cells knock down of [HDAC6 + HDAC2] or [HDAC6 + HDAC10] significantly enhanced pazopanib lethality whereas knock down of [HDAC6 + HDAC1] or [HDAC6 + HDAC3] were less effective." (PMID 29137331, 2017). "Similarly, in melanoma, HDAC10 inhibitors were shown to enhance tumor sensitivity to BRAF inhibitors by upregulating SPARC expression, a key factor in modulating the tumor microenvironment." (PMID 40657362, 2025). "The transient depletion of HDAC10 may lead to severe mitotic catastrophe and cell cycle arrest in 2D culture in some melanoma lines." (PMID 38650694, 2024). "Similar results were obtained when other melanoma cell lines were depleted of HDAC10." (PMID 38650694, 2024). "Thus, HDAC10 is the major HDAC that suppresses SPARC expression in melanoma cells." (PMID 38650694, 2024). "Thus, HDAC10 depletion may influence melanoma cell fate in diverse ways depending on the cellular context." (PMID 38650694, 2024). "HDAC10 restores melanogenesis by deacetylating paired box protein 3 (Pax3) and KRAB-associated protein 1 (KAP1), which relieves the repressed promoters of microphthalmia-associated transcription factor (MITF) as well as tyrosinase-related protein 1 (TRP-1) and TRP-2 in melanoma cells." (PMID 33997894, 2021). "In contrast, treatment with PLX4032 didn’t significantly change the expression patterns of HDAC10 and SPARC in BRAF WT melanoma cells (SK-MEL-2 and WM3918)." (PMID 38650694, 2024). "HDAC10 depletion and resultant SPARC upregulation repress melanoma cell growth primarily by activating AMPK signaling and inducing autophagy." (PMID 38650694, 2024).
melanoma (continued). "Our work also establishes the HDAC10-SPARC axis as a critical regulator in melanoma cell growth and BRAFi resistance, offering insight into potential therapeutic targets for melanoma and related malignancies." (PMID 38650694, 2024). "Depletion of HDAC10 and the subsequent upregulation of SPARC activate AMPK signaling and induce autophagy, ultimately suppressing melanoma cell growth and attenuating resistance to BRAF inhibitors." (PMID 38650694, 2024). "Consistent with the detectable activity of HDAC10 on histones, a genetic knockout of HDAC10 in non-small cell lung cancer (NSCLC) and melanoma cells augmented the acetylation of histone H3 at K9/K27 and the expression of the cell cycle regulator cyclin A in certain tumor cells." (PMID 40301616, 2025). "In this scenario, HDAC10 may work similarly to HDAC8 which modulates p300 function, and increases H3K27ac and chromatin accessibility at Jun-transcriptional sites in melanoma cells." (PMID 38650694, 2024). "However, in melanoma cells characterized by high SPARC expression, HDAC10 depletion significantly repressed colony and spheroid growth." (PMID 38650694, 2024). "Furthermore, our work shows that HDAC10 depletion and resultant SPARC upregulation led to repressive melanoma cell growth and increased vulnerability to BRAF inhibition in resistant cells." (PMID 38650694, 2024). "Notably, the expression dynamics of both HDAC10 and SPARC are influenced by the BRAF activity state in BRAF mutant melanoma cells (A375 and WM793)." (PMID 38650694, 2024). "Therefore, the HDAC10-SPARC axis may regulate the colony and spheroid growth of melanoma cells by interfering with some of these pathways." (PMID 38650694, 2024).
cervical cancer (6 papers, 2016 to 2022). A primary or metastatic malignant neoplasm involving the cervix. "Also, poor HDAC10 expression was linked to oncogenesis in cervical cancer via targeting microRNAs and the metastasis via targeting the expression of matrix metalloproteinase." (PMID 35075362, 2022). "Notably, over-expression of HDAC10 has been associated with better prognosis of cervical cancer." (PMID 36100870, 2022). "The purpose of this study is to explore the effects of HDAC10/miR-223/EPB41L3 axis in cervical cancer." (PMID 35075362, 2022). "HDAC10 was poorly expressed in cervical cancer and precancer lesions, while miR-223 was highly expressed in cervical cancer." (PMID 35075362, 2022). "Herein, cervical cancer, precancer lesions, and normal cervical tissues were collected to test the expression level of HDAC10, miR-223, and EPB41L3." (PMID 35075362, 2022). "For exploring the biological functions of dysregulated HDAC10 upon cervical cancer cells, we analyzed the cell viability and colony-forming ability of cervical cancer cells after the treatment of overexpressed HDAC10." (PMID 35075362, 2022). "miR-1908-5p targets HDAC10 to promote the growth, invasion, and metastasis of cervical cancer cells (Ca-Ski, SiHa, and C-4I)." (PMID 35463352, 2022). "The mechanism of HDAC10, miR-223, and EPB41L3 was interpreted in cervical cancer cells after HDAC10, miR-223, or EPB41L3 expression was altered." (PMID 35075362, 2022). "The results manifested that the protein expression level of HDAC10 was low in cervical cancer tissues and cells." (PMID 35075362, 2022). "HDAC10 depressed the invasion property and tumorigenesis of cervical cancer via downregulating miR-223 and subsequently targeting EPB41L3." (PMID 35075362, 2022). "Taken together, miR-1908 increases aggressive behavior of cervical cancer cells through targeting HDAC10." (PMID 36100870, 2022). "For clarification of HDAC10-mediated mechanism in the progression of cervical cancer, the current study detected the expression level of HDAC10 in 20 cervical cancer cases, 20 LSIL cases, 20 HSIL cases, and normal cervical tissues." (PMID 35075362, 2022). "In conclusion, our study provides evidence that HDAC10 downregulates the expression miR-223 in cervical cancer and subsequently targets EPB41L3." (PMID 35075362, 2022). "In this present study, we explored the vital role of HDAC10 in suppressing the development of tumorigenesis in cervical cancer." (PMID 35075362, 2022). "In cervical cancer samples, the expression of miR-1908 has been inversely correlated with transcript levels of HDAC10." (PMID 36100870, 2022). "Then, we conducted the RT-qPCR assay and western blot assay to analyze the HDAC10 expression level in cervical cancer in both the tissue and the cells." (PMID 35075362, 2022). "Although the tumorigenesis of cervical cancer (CC) has been widely investigated and recognized, the study of the systematic impact of histone deacetylase 10 (HDAC10), microRNA, and downstream molecular mechanisms in CC is still limited." (PMID 35075362, 2022). "The HDAC10 expression level is downregulated in cervical carcinoma tissues compared to normal cervical tissues." (PMID 35075362, 2022). "The Ki-67 expression level is lower in oe-HDAC10 group when compared with the oe-NC control group, which means that the upregulation of HDAC10 inhibited the proliferation of cervical carcinoma." (PMID 35075362, 2022). "Furthermore, miR-223 mimic or downregulation of EPB41L3 functionally reversed the effects of upregulation of HDAC10 upon the cervical cancer cells, including the cell viability, colony-forming ability, apoptosis, cell migration, and cell invasion." (PMID 35075362, 2022). "Also, the results demonstrated that HDAC10 inhibited the ability of tumorigenesis in cervical cancer in vivo via downregulating miR-223 and subsequently targeting EPB41L3." (PMID 35075362, 2022).
cervical cancer (continued). "Furthermore, we conducted the analysis about the HDAC10 expression in cervical cancer via the endocervical adenocarcinoma (CESC)-TCGA database." (PMID 35075362, 2022). "HDAC10 was reported to negatively regulate the progression of cervical cancer by miR-1908." (PMID 35075362, 2022). "In addition, our data reveal that cervical cancer cell with overexpressed HDAC10 exhibited cell viability and colony-forming ability, suggesting that HDAC is connected with cancer progression." (PMID 35075362, 2022). "We previously reported that HDAC10 inhibits the metastasis of cervical cancer." (PMID 27449083, 2016). "Besides, ectopic expression of HDAC10 in cervical cancer cells could reverse the effect of miR-1908 to some extent." (PMID 36100870, 2022). "Researchers have begun to elucidate the function of HDAC10 in recent years and determined that it plays a role in homologous recombination, promotes autophagy and survival in neuroblastoma cells, suppresses cervical cancer metastasis and facilitates the cell cycle." (PMID 27449083, 2016). "In cervical cancer HDAC1, HDAC10, SIRT6, SIRT7 are always present; whist in colorectal cancer is HDAC10, SIRT6, SIRT7." (PMID 30691229, 2019). "However, how the crosstalk network of HDAC10, miR-223, and EPB41L3 regulates the progression of cervical cancer is still unclear." (PMID 35075362, 2022). "The study clarifies that HDAC10 inhibits cervical cancer by downregulating miR-223 and subsequently targeting EPB41L3 expression, which might provide a new insight for management upon cervical cancer and precancer lesions." (PMID 35075362, 2022).
ovarian carcinoma (6 papers, 2018 to 2023). A malignant neoplasm originating from the surface ovarian epithelium. "Low HDAC10 levels correlate with platinum sensitivity of tumors, and inhibition of HDAC10 enhances the efficacy of platinum chemotherapy in primary ovarian cancer cells." (PMID 36505774, 2022). "HDAC10 is a histone deacetylase that regulates melanogenesis in ovarian cancer patients." (PMID 37441601, 2023). "HDAC10 mRNA levels correlate with the platinum sensitivity of ovarian carcinoma cells." (PMID 32373519, 2020). "We ultimately constructed a histone acetylation modulator-related signature containing 10 histone acetylation modulators, among which HDAC1, HDAC10, and KAT7 can act as independent prognostic factors for ovarian cancer and are related to poor prognosis." (PMID 36172179, 2022). "Moreover, polyamines are known to modulate DNA conformation by strongly binding to the DNA helix, and recently identified roles of HDAC10 include regulation of DNA mismatch and DSB repair in various cancer types such as ovarian carcinoma." (PMID 29947893, 2018).